NDUFS4 (NADH:ubiquinone oxidoreductase subunit S4)
Description:
Accessory subunit of the mitochondrial membrane respiratory chain NADH dehydrogenase (Complex I), that is believed not to be involved in catalysis. Complex I functions in the transfer of electrons from NADH to the respiratory chain. The immediate electron acceptor for the enzyme is believed to be ubiquinone.
Synonyms: CI-18 kDa; CI-AQDQ; AQDQ; CI-18; MC1DN1
Tractability: Small molecule: an approved drug acts on it; a structure with a bound ligand is known. Antibody: UniProt places it where antibodies can reach, with high confidence. PROTAC: its protein half-life has been measured.
Gene: Protein-coding gene on chromosome 5 (53,560,633 to 53,683,338, forward strand). Ensembl gene ENSG00000164258.
Subcellular location: Mitochondrion inner membrane
Subcellular location (Human Protein Atlas): Mitochondria; Calyx; Equatorial segment; Perinuclear theca
Pathways (Reactome):
Metabolism: Complex I biogenesis; Respiratory electron transport
Gene Ontology:
Molecular function: NADH dehydrogenase (ubiquinone) activity; protein binding
Biological process: brain development; mitochondrial respiratory chain complex I assembly; reactive oxygen species metabolic process; regulation of protein phosphorylation; response to cAMP; aerobic respiration; mitochondrial electron transport, NADH to ubiquinone; proton motive force-driven mitochondrial ATP synthesis; respiratory electron transport chain; electron transport chain; proton transmembrane transport
Cellular component: mitochondrial inner membrane; mitochondrion; respiratory chain complex I
Genetic constraint (gnomAD): Loss-of-function variants: 24 observed, 22.2 expected, observed/expected ratio (o/e) 1.08, 90% interval 0.78 to 1.52. The upper end of that interval is the gene's LOEUF score, 1.52, which puts it in group 6 of 6, group 1 being the genes least tolerant of losing a copy. Missense variants: 210 observed, 208.72 expected, observed/expected ratio (o/e) 1.01, 90% interval 0.9 to 1.13. Synonymous variants: 91 observed, 72.15 expected, observed/expected ratio (o/e) 1.26, 90% interval 1.06 to 1.5.
Gene-disease validity (ClinGen):
ClinGen rates the evidence that NDUFS4 causes each of these diseases.
Leigh syndrome (autosomal recessive): Definitive. A progressive neurological disease defined by specific neuropathological features associating brainstem and basal ganglia lesions.
mitochondrial disease (autosomal recessive): Definitive.
Homologues: Orthologues: chimpanzee NDUFS4 (100% identical), macaque NDUFS4 (96% identical), pig NDUFS4 (91% identical), rabbit NDUFS4 (89% identical), mouse Ndufs4 (88% identical), rat Ndufs4 (77% identical), tropical clawed frog ndufs4 (75% identical), zebrafish ndufs4 (67% identical), Caenorhabditis elegans lpd-5 (45% identical), Drosophila melanogaster ND-18 (44% identical). Paralogues in human: WDR93 (19% identical).
Diseases named in the same sentence as NDUFS4 in open-access papers:
NDUFS4 is named in the same sentence as 89 diseases in open-access papers, as found by Europe PMC text mining. Sharing a sentence is not in itself a finding about the gene and the disease. The quoted sentences say what the papers report.
Leigh syndrome (94 papers, 2012 to 2026). "Leigh syndrome is a fatal pediatric neurodegenerative disease caused by mitochondrial dysfunction, which can be modeled in the Ndufs4 KO mouse with mitochondrial respiratory chain complex I (CI) deficiency." (PMID 41704780, 2026). "The therapeutic potential of vatiquinone in vivo was assessed using the tamoxifen-induced mouse model for GPX4 deficiency and the Ndufs4 knockout mouse model of Leigh syndrome." (PMID 39930437, 2025). "Knockout (KO) studies and naturally occurring mutations show that disruption of the accessory subunit NDUFS4 leads to the severe multisystemic progressive neurodegenerative disorder Leigh syndrome." (PMID 40667359, 2025). "Leigh syndrome is characterized by overt symmetrical lesions in the brainstem and basal ganglia, areas particularly vulnerable to Ndufs4 deficiency in mice." (PMID 41321311, 2025). "Lastly, we analyzed T-cell effector functions in a patient with Leigh syndrome and recurrent infections due to an NDUFS4 loss-of-function (LOF) gene variant." (PMID 41573538, 2025). "According to a systematic review of 195 Leigh syndrome patients with 24 different gene variants, only 22 cases involving NDUFS4 mutations have been reported worldwide." (PMID 41573538, 2025). "NDUFS4 deficiency in humans and murine models, is known to cause Leigh syndrome, a progressive disorder characterized by neurological regression with motor and neuroradiological evidence of basal ganglia involvement." (PMID 41573538, 2025). "Our recognition that NDUFS4 deficiency impairs T-cell function offers a novel perspective on Leigh syndrome management, especially given that immunological assessment is often overlooked in these patients." (PMID 41573538, 2025). "Complex I deficiency is the leading cause of Leigh syndrome, with mutations in the nuclear gene NDUFS4 being the most common cause of complex I-associated Leigh syndrome." (PMID 39788934, 2025). "Loss of function mutations of NDUFS4 resulted in Leigh syndrome, which is a progressive neurodegenerative disease and characterized by mitochondrial oxidative stress, inflammation and aberrant mitochondrial dynamics." (PMID 40767000, 2025). "Although no treatments are available for complex I deficiencies, chronic hypoxia improves lifespan and function in a mouse model of the severe mitochondrial disease Leigh syndrome caused by mutation of complex I subunit NDUFS4." (PMID 40667359, 2025). "The genetic causes of Leigh syndrome are heterogeneous, but a widely studied mouse model has been developed by knocking out Ndufs4, a subunit of complex I." (PMID 39858433, 2024). "The therapeutic potential of vatiquinone in vivo was assessed using tamoxifen-induced mouse model for GPX4 deficiency and the Ndufs4 knockout mouse model of Leigh syndrome." (PMID 38883711, 2024). "Mutations in the NDUFS4 subunit of respiratory complex I lead to neurological mitochondrial disorders such as Leigh syndrome in pediatric patients." (PMID 38177503, 2024). "This animal shares a causal genetic defect with a subset of human Leigh syndrome patients (complete loss of NDUFS4) and displays the major sequelae of the human disease." (PMID 38883711, 2024). "In mice, knockout of Ndufs4 specifically in the brain recapitulates the severe motor, seizure, neuroinflammatory and lifespan phenotypes associated with Leigh syndrome, indicating that symptoms are driven by loss of complex I activity in the nervous system." (PMID 37399212, 2023). "Defects in NDUFS4, encoding a structural/assembly component of ETC CI, are one cause of Leigh syndrome, and the Ndufs4-deficient Ndufs4 knockout (Ndufs4(−/−)) mouse provides a remarkably close model for the human disease." (PMID 37770252, 2023). "Loss-of-function mutations in NDUFS4 leads to complex-I deficiency causing a neuromuscular disease, Leigh syndrome and is also involved in cardiomyopathies." (PMID 37276142, 2023).
Leigh syndrome (continued). "The Ndufs4 gene, which encodes a supernumerary subunit of complex I, is a mutational hotspot in Leigh syndrome patients." (PMID 37725617, 2023). "Nearly 35% of Leigh Syndrome cases can be caused by various mutations affecting Complex I including NDUFS4 and several other iron-sulfur proteins on the redox-active peripheral arm." (PMID 36799301, 2023). "In a Ndufs4 knockout mouse model of Leigh syndrome and complex I deficiency, the selective inactivation of these striatal neurons led to progressive motor impairment." (PMID 34716721, 2022). "One of these subunits, human NDUFS4, is required for MCI assembly, and misregulation of NDUFS4 has been linked with Leigh syndrome and cardiomyopathy." (PMID 35557603, 2022). "Johnson and colleagues successfully extended the survival of a mouse model of Leigh syndrome, which was deficient in Ndufs4 of complex I, by chronic administration of the mTOR inhibitor, rapamycin." (PMID 35681427, 2022). "The Ndufs4−/− KO mice mimic the human Leigh syndrome, which is normally caused by severe mitochondrial dysfunction, most commonly due to mitochondrial complex I deficiency." (PMID 34680998, 2021). "NADH Dehydrogenase (Ubiquinone) Fe-S protein 4 (Ndufs4) is one of the subunits of mitochondrial complex I and its mutation in human is associated with Leigh syndrome." (PMID 34040028, 2021). "Upon genetic investigation, the patient was found to carry a novel homozygous mutation in the NDUFS4 gene, thus adding to the heterogeneity of Leigh syndrome clinical presentation." (PMID 34484776, 2021). "AAV‐based gene therapy strategies have been trialled in a Ndufs4−/− mouse model of Complex I deficient Leigh syndrome." (PMID 32618366, 2021). "CI deficiency, caused by a deletion in the nuclear encoded gene Ndufs4, results in Leigh syndrome, which is the most common mitochondrial disease in children." (PMID 30520688, 2019). "In Ndufs4-KO mice, a mouse model of Leigh syndrome, we found that Complex I deficiency led to declines in NAD+ levels and NAD+ redox imbalance." (PMID 30816177, 2019). "Nevertheless, in contrast to the Ndufs4 KO mice, another mouse model of Leigh syndrome in which a low heart rate was associated with the brainstem pathology, the heart rate was normal in Coq9R239X mice." (PMID 27856619, 2017). "Patients with mutations in NDUFS4 will develop Leigh syndrome, a neurodegenerative disease with onset in infancy or early childhood, and possess a CI assembly defect along with a severe abolishment of CI activity." (PMID 28533980, 2017). "One unexpected finding was a high carrier frequency (1/13) for the c.393dupA mutation in NDUFS4 causing Leigh syndrome." (PMID 27247959, 2016). "Loss of the gene that encodes this subunit (NDUFS4) in mice replicates Leigh syndrome, a devastating human neurological, mitochondrial-linked disease." (PMID 26635618, 2015). "A mouse model of complex I deficiency created by knocking out NDUFS4, a nuclear encoded complex I subunit, presented severe neurodegeneration (Leigh syndrome-like phenotype) and death within the first 7 weeks." (PMID 24684792, 2014). "Additionally, T cells from a patient with Leigh syndrome induced by NDUFS4 loss-of-function were analyzed." (PMID 41573538, 2025). "NDUFS4 variants are an extremely rare cause of Leigh syndrome." (PMID 41573538, 2025). "Importantly, T cells from a single Leigh syndrome patient with an NDUFS4 loss-of-function variant showed similar defects, including impaired activation and proliferation." (PMID 41573538, 2025). "Further, we implicated NDUFS4 in our neurodegeneration predictive models, which has been connected to both AD and in neurodegeneration associated with the mitochondrial disorder Leigh Syndrome." (PMID 37834458, 2023). "Moreover, evidences of the contribution of altered Fe homeostasis to the pathogenetic mechanisms of Leigh syndrome associated with the loss of the Fe-S binding complex I subunit NDUFS4 have been found." (PMID 35663391, 2022).
Leigh syndrome (continued). "Knockout of both alleles of Ndufs4 in the most widely used exon 2 model leads to early mortality at approximately 2 months of age accompanied by a necrotizing encephalopathy that resembles human Leigh syndrome and display approximately 50% complex I activity." (PMID 35338200, 2022). "Additionally, humans with a mutation of NDUFS4 genes, including patients with Leigh syndrome, have repeatedly shown an increased blood lactate level." (PMID 35845998, 2022). "In recent pre-clinical work, we have shown that pharmacologic agents targeting the immune system can prevent disease in the Ndufs4(KO) model of Leigh syndrome, indicating that the immune system plays a causal role in the pathogenesis of at least this form of mitochondrial disease." (PMID 36056365, 2022). "Most studies on the effect of genetic alteration of complex I in mice have used mutation or deletion of the accessory subunit gene Ndufs4 which is associated with phenotypes resembling human mitochondrial diseases such as Leigh syndrome and Leber Hereditary Optic Neuropathy41,42." (PMID 35338200, 2022). "A 2 year-old Leigh syndrome patient homozygous for the known pathogenic c.355G > C (pAsp119His) mutation in NDUFS4 responded strikingly well to mTOR inhibition therapy, with a reversal of brain lesions and striking recovery of gross motor function which persisted through ~ 20 months of therapy." (PMID 36056365, 2022). "Mutation of NDUFS4 causes Leigh syndrome and cardiomyopathy." (PMID 35557603, 2022). "The pathophysiology of NDUFS4-linked Leigh syndrome is increasingly well understood." (PMID 34069703, 2021). "In 2013, Johnson and colleagues showed that intraperitoneal (i.p.)administration of high doses of rapamycin dramatically reduced the gliosis and the histopathological signs on a mouse model of Leigh syndrome due to mitochondrial complex I deficiency (Ndufs4−/− model), thus increasing the survival." (PMID 30898651, 2019). "Here we tested whether disruption of S6K1 can recapitulate the beneficial effects of mTORC1 inhibition in the Ndufs4 knockout (NKO) mouse model of Leigh Syndrome caused by Complex I deficiency." (PMID 28919908, 2017). "Therefore, Ndufs4 deletion mice are excellent models with which to study the phenotypes and molecular mechanisms of mitochondrial complex I deficiency and Leigh syndrome." (PMID 28533980, 2017). "The NDUFS4 gene encodes an 18-kD subunit of mitochondria complex I, and mutations in this gene lead to the development of a severe neurodegenerative disease called Leigh syndrome (LS) in humans." (PMID 28533980, 2017). "However, it may be interesting to study how mitochondrial defects impact the presynapse in patients with NDUFS4 mutations and in other genetic forms of Leigh Syndrome." (PMID 37239850, 2023). "Homozygous mutations in NDUFS4 are responsible for one of the most severe forms of Leigh syndrome (LS), an inherited neurodegenerative condition, characterized by poor prognosis as patients typically die before 3 years of age." (PMID 30979712, 2019). "Hence, we assessed mitochondrial function in neurologically relevant primary cell lines from a CI (complex I) deficient Ndufs4 KO (knockout) mouse (Ndufs4fky/fky) modelling aspects of the mitochondrial disease LS (Leigh syndrome), as well as MEFs (mouse embryonic fibroblasts)." (PMID 25312000, 2014). "The Ndufs4 knockout (KO) mouse model of Leigh syndrome (LS), which lacks a critical CI subunit, exhibits severe cardiac abnormalities secondary to encephalomyopathy." (PMID 41532297, 2026). "In this regard, the epileptic phenotype commonly worsens as disease progresses in individuals with Leigh syndrome and in NDUFS4-KO mice." (PMID 41321311, 2025). "Mice missing the complex I subunit Ndufs4 of the electron transport chain are widely used as a leading animal model of Leigh syndrome, a pediatric neurodegenerative disorder that leads to premature death." (PMID 40467953, 2025).
Leigh syndrome (continued). "After optimizing dosing strategies, we evaluated the efficacy of HypoxyStat in the Ndufs4 KO mouse model of Leigh syndrome." (PMID 39965572, 2025). "To test the efficacy of vatiquinone in the context of Leigh syndrome, we used the Ndufs4(−/−) mouse model of the disease." (PMID 38883711, 2024). "The third one is gene therapy targeting complex I, such as the preclinical research and clinical trial for Leber’s hereditary optic neuropathy targeting ND4 gene and the gene therapy by AAV-Ndufs4 in Leigh syndrome mouse model of systemic Ndufs4-knockout." (PMID 38594619, 2024). "Brain tissue hyperoxia observed in SqorΔN/ΔN mice is similar to the phenotype of mice that are deficient in the mitochondrial complex I subunit NADH:ubiquinone oxidoreductase subunit S4 (NDUFS4), another mouse model of Leigh syndrome." (PMID 38870029, 2024). "In contrast to SSMD, a robust a well-established mammalian model for Leigh syndrome is available, the Ndufs4(−/−) mouse." (PMID 38883711, 2024). "In the Ndufs4 KO Leigh syndrome model, high NADH levels in the brain imply a connection between NADH reductive stress and disease severity." (PMID 39858433, 2024). "Recent studies have also shown that Leigh syndrome, a mitochondrial disorder, can be treated with NMN supplementation in Ndufs4-KO mice, a mouse model of Leigh syndrome." (PMID 37548938, 2024). "Utilizing this technique, we quantified NADH and NAD+ levels in fibroblasts derived from pediatric patients and in a Leigh syndrome mouse model in which mitochondrial respiratory chain complex I subunit Ndufs4 is knocked out (KO)." (PMID 39858433, 2024). "We previously showed that hypoxia can both prevent and reverse neurological disease in the Leigh syndrome Ndufs4 KO mouse model." (PMID 37260376, 2023). "Mutations in the complex I genes NDUFS4 and NDUFS1 commonly lead to Leigh syndrome, an aggressive form of complex I deficiency." (PMID 37399212, 2023). "A global and Nestin-specific conditional knockout of complex I subunit Ndufs4 in mice, modelling key features of Leigh syndrome, resulted in early-onset tonic-clonic seizures in a proportion of animals." (PMID 37298649, 2023). "Moreover, mice with mitochondrial Complex I subunit Ndufs4 deficiency (Ndufs4−/−) developed mitochondrial dysfunction and bradyarrhythmia resembling Leigh syndrome (LS)." (PMID 36899814, 2023). "We exposed Ndufs4(−/−) mice, a model of Leigh syndrome, to isoflurane (0.2–0.6%), oxygen 100%, or air." (PMID 37770252, 2023). "Mutations in NDUFS4 gene, encoding NADH dehydrogenase (ubiquinone) iron-sulfur protein 4, result in compromised activity of mitochondrial complex I, causing Leigh syndrome- the most common infantile mitochondrial encephalopathy." (PMID 36471396, 2022). "Perturbations of the glutamine/glutamate/αKG metabolic axis were also found in the Ndufs4 KO mouse model of Leigh syndrome while being rescued by mTOR inhibition with rapamycin." (PMID 35884972, 2022). "Using an Ndufs4−/− mouse model for Leigh syndrome, we showed that partial ablation of microglia by Pexidartinib initiated at the symptom onset improved neurological function and significantly extended lifespan." (PMID 36741056, 2022). "To elucidate the role of microglia, we applied a widely used mouse model of Leigh syndrome with germline homozygous deletion of exon 2 of mitochondrial complex I subunit Ndufs4 (Ndufs4−/−)." (PMID 36741056, 2022). "Several studies have shown that administration of human NDUFS4 coding sequence by AAV2/9 and/or AAV-PHP.B vectors improved clinical phenotype and prolonged the lifespan in Ndufs4 − / − mice representing a model of Leigh syndrome." (PMID 36471396, 2022). "Rapamycin inhibits mTOR and was shown to prolong lifespan of the Ndufs4−/− Leigh syndrome mouse model." (PMID 32618366, 2021). "Direct injury of mitochondrial respiratory chain (RC) complex I by Ndufs4 subunit mutations results in complex I deficiency (CID) and a progressive encephalomyopathy, known as Leigh syndrome." (PMID 34677373, 2021).